IL4 (interleukin 4)
Diseases named in the same sentence as IL4 in open-access papers (continued):
Sharing a sentence is not in itself a finding about the gene and the disease.
eosinophilia (351 papers, 2004 to 2026). "IL-4/13 blockade in AD treatment has been linked to eosinophilia, conjunctivitis, arthritis, and facial erythema, likely due to a shift toward IL-17-driven inflammation." (PMID 41481132, 2026). "These chemokines are induced by Th2 cytokines (IL-4 and IL-13) and work synergistically with IL-5 to drive eosinophilia, a hallmark of helminth infections." (PMID 40872306, 2025). "The Th2 cells and their cytokines, interleukin-4 (IL-4) and interleukin-5 (IL-5), promote the production of IgE and eosinophilia, which are critical components of the atopic predisposition." (PMID 40831866, 2025). "The cytokines such as IL-4, IL-5, and IL-13 are released causing eosinophilia and the pro-inflammatory cytokines like IFN-γ, TNF, IL-6, and IL-15 are increased promoting systemic inflammation." (PMID 41229508, 2025). "Elevated levels of IL-4, IL-5, and IL-13 are noted in patients and are associated with increased peripheral eosinophilia and IgE levels, which are common features of this disease." (PMID 39139309, 2024). "IL-5 represents the key driver of eosinophilia, while the Il-4/IL-13 inflammatory pathway is strongly associated with FeNO, which, in turn, correlates with eosinophilic inflammation in the airways." (PMID 37947596, 2023). "This exposure was associated with increased levels of total IgE, asIgE, IL‐4, IL‐5 in blood and nasal eosinophilia as determined by histological examination." (PMID 34965026, 2022). "Th2 cells are classically regarded as important effector cells that produce the hallmark cytokines IL-4 and IL-13, but also IL-3 and IL-5 that promote basophilia and eosinophilia, respectively." (PMID 35844529, 2022). "As Th2-mediated responses that underlie airway eosinophilia and airway hyperresponsiveness have been linked to IL-4, IL-5, and IL-13, we measured the levels of these cytokines in the BAL of OVA-exposed mice." (PMID 34744763, 2021). "A type 2 immune response was associated with exposure, with increased interleukin-4 (IL-4) production, IL-5 transcription, and eosinophilia." (PMID 28993458, 2018). "AD is characterized as a Th2 disease with the abundant production of Th2 cytokines, such as interleukin IL-4, IL-5 and IL-13 associated with eosinophilia and elevated serum IgE level." (PMID 28434120, 2017). "Mice infected with helminths inducing eosinophilia, elevations in IL-4, IL-13 and other cytokines associated with alternative activation of macrophages (M2) in white adipose tissue (e.g. IL-4, IL-13) show improved glucose tolerance and reduced fat mass." (PMID 27666719, 2016). "Helminth infections were strongly associated with eosinophilia and hyper-IgE as well as with a Th2-polarized response (increased levels of IL-13, IL-10, and IL4/IFN-γ ratios and decreased levels of IFN-γ)." (PMID 27882241, 2016). "IL-33 is known to contribute to AHR since animal studies demonstrated that intranasally administered IL-33 results in an AHR-association with eosinophilia, goblet cell hyperplasia, and accumulation of IL-4, −5 and −13 in the lungs." (PMID 25849971, 2015). "IL-4 and IL-13 are potent inducers of eotaxin chemokines that can explain the eosinophilia associated with Th2 responses." (PMID 24693457, 2014). "Anti-inflammatory cytokines such as IL-4 and IL-10 are associated with helminthiasis and eosinophilia and a limited number of studies have reported the detection ofsuch cytokines in CV disorders." (PMID 25303100, 2014). "The Th2-type immune responses associated with schistosomiasis include elevated IL-4 and peripheral blood eosinophilia." (PMID 23824043, 2013). "In this study, RSV G peptide vaccine, when given at the same time as FI-RSV vaccination led to significant decreases in four measures of enhanced disease; i.e. pulmonary cell infiltration, eosinophilia, IL-4 levels and weight loss." (PMID 24376637, 2013).
eosinophilia (continued). "In onchocerciasis, the presence of IL-10 is clearly associated with a protective immunological scenario: high IgG4, IL-10 and Treg are associated with low pathology whereas high levels of IgE, IL-4 and eosinophilia are common in patients with severe pathology." (PMID 22509424, 2012). "Expression of IL-4, IL-5 and IL-13 are associated with airway hypersensitivity, eosinophilia, abundant plasma cells and pathological changes in the lungs." (PMID 21765962, 2011). "In AD, most side effects—such as conjunctivitis, eosinophilia, and arthritis—are linked to IL-4 and IL-13 blockade, which may lead to increased IL-17 activity." (PMID 41481132, 2026). "The characteristic Th2-related cytokines (Il4, Il5, Il13) were markedly increased in AD-like lesions, while Il4 and Ccl11 expression was elevated to various extent in PN-like lesions appeared to be associated with dermal eosinophilia." (PMID 41229431, 2025). "TH2-associated cytokines such as IL-4, IL-5, and IL-13, which are often detectable in the presence of eosinophilia, may play a role in EDHM’s pathogenesis." (PMID 39219952, 2024). "In addition, the IL-4, IL-5 and Th2 responses associated with eosinophilia have been described in C. neoformans pneumonia, but little is known about these populations during C. gattii infection." (PMID 36145419, 2022). "Finally, in an ovalbumin-induced murine model of allergic airway disease, NK-deficient mice had decreased airway inflammation and eosinophilia, decreased secretion of IL-4, IL-5, and IL-13, as well as diminished OVA-specific antibody production." (PMID 36250466, 2022). "Here we show that Hp‐TGM could alleviate airway and lung tissue eosinophilia, in association with control of IL‐5 and IL‐33 cytokine levels at 24 h, or either IL‐4 and eotaxin‐1, or IL‐4 and IL‐13 responses in T‐cell mediated models." (PMID 35758054, 2022). "Interestingly, myeloid-specific IL4Rα-deficient (mye-IL4Rα−/−) mice had significantly reduced eosinophilia in the airspaces that was associated with reduced levels of IL-4 and IL-5 in the bronchoalveolar lavage fluid (BALF)." (PMID 34326406, 2021). "Our findings with administration of t-TUCB are similar to those from a previous study where OVA-challenged mice administered with t-TUCB demonstrated increased levels of EETs (5,6-, 11,12-, and 14, 15-) associated with decreased eosinophilia and reduced IL-4 and IL-5 levels." (PMID 31611798, 2019). "In particular, administration of somatic extract of M. marshalli during OVA sensitization resulted in reduction of Th2 associated immune responses including IL-4 and IL-13 and IgG1, as well as inflammatory cells infiltration, eosinophilia and goblet cells hyperplasia." (PMID 28494800, 2017). "Interestingly, expression of GATA-3, CCR3, -4, -8, and ST2L, and the generation of blood eosinophilia, is intact in mice doubly deficient in both IL-4 and IL-13." (PMID 18315837, 2008). "Therefore, the inhibition of asthmatic symptoms by PS + CR may be associated with the reduction of IL-4 and IL-5 production and the eosinophilia aggregation into the lungs, as comparable to DEXA (3 mg/kg), at oral dose level of 1,000 mg/kg, once again." (PMID 32190091, 2020). "Dupilumab (targeting IL-4/IL-13) and mepolizumab (targeting IL-5) have shown promising results in reducing mass size and eosinophilia in patients who respond poorly to conventional therapies." (PMID 41527674, 2026). "As a matter of fact, in Western Countries, CRSwNP is well known to be predominantly characterized by Type 2 inflammation with pronounced eosinophilia and the presence of high levels of Type 2 cytokines, such as IL-4, IL-5 and IL-13." (PMID 41295249, 2025). "Previous animal studies have shown that reduced IL-4 levels correspond with decreased eosinophilia, emphasizing its role in eosinophil regulation." (PMID 40333150, 2025).
eosinophilia (continued). "While markers for identifying the T2-high phenotype are well established, IL-4, IL-5, IL-13, IgE, eosinophilia, and high FeNO levels, evidence for T2-low biomarkers remains limited." (PMID 40003269, 2025). "It is well established that eosinophilia is related to type-2 inflammation, with eosinophils produced in response to IL-5 and further regulated in response to IL-4 and IL-1330." (PMID 40846755, 2025). "Eosinophilia on dupilumab is likely related to downstream cytokine effects from IL-4 and IL-13 blockade." (PMID 40863432, 2025). "Th2 cells are main producers of IL-4 and IL-13 and were thought to be the crucial driver of eosinophilia." (PMID 40276331, 2025). "Allergic Asthma (AA) is characterized by elevated levels of IgE; type 2 cytokines, including interleukin-4 (IL-4) and IL-13; Th17 cytokines, such as interleukin-17A-F, IL-21, and IL-22; mucus hypersecretion; eosinophilia; and airway hyperresponsiveness (AHR)." (PMID 41515303, 2025). "Eosinophilia remains one of the treatable traits; recent trials with anti–IL-4/IL-13 therapies have shown improved exacerbation outcomes in tobacco-related COPD." (PMID 40959786, 2025). "The type 2 immune cytokines IL-4 and IL-13 are essential for eosinophil recruitment to the allergic lung, as depletion of both cytokines abolishes eosinophilia." (PMID 40276331, 2025). "Specifically, Th2-mediated inflammation is predominant, characterized by elevated interleukin (IL)-4, IL-5, and IL-13, leading to eosinophilia, IgE overproduction, and skin barrier dysfunction." (PMID 40831866, 2025). "Mechanistically, allergen-sensitized Th2 cells produce pro-inflammatory cytokines such as IL-4, IL-5, and IL-13, thereby driving airway eosinophilia and chronic inflammation." (PMID 41422349, 2025). "Patients with AD typically exhibit elevated serum IgE levels, peripheral eosinophilia, impaired cellular immunity, and increased IL-4 production, all contributing to disease pathogenesis." (PMID 40722624, 2025). "Activated Th2 cells release cytokines, including IL-4, IL-13, and IL-5, inducing eosinophilia in tissues and peripheral blood." (PMID 39521708, 2025). "SLIT reduced TNSS, TMS, VAS scores, IL‐4, IL‐17, eosinophilia percentage (EOS%), and specific immunoglobulin E (sIgE) levels, while increasing INF‐γ, IL‐10, and sIgG4." (PMID 39739782, 2025). "The innate response to STHs comprises the release of cytokines, such as IL-4, IL-5, and IL-13, which drive eosinophilia, mast cell activation, and IgE production, which are key mechanisms required for the expulsion of parasites." (PMID 40872306, 2025). "Type 2 inflammation is driven by the cytokines IL-4, IL-13, and IL-5, leading to eosinophilia, elevated IgE levels, and activation of eosinophils and mast cells within tissues." (PMID 41210306, 2025). "Although dupilumab is generally well tolerated, eosinophilia due to inhibition of IL-4-/IL-13–mediated chemokines and adhesion molecules that assist with eosinophil migration from blood into tissue has been observed." (PMID 40778341, 2025). "IL-4 upregulation induces lung inflammation characterized by BAL fluid eosinophilia, airway hyperresponsiveness (AHR), and an increase in the number of goblet cells in mouse lungs." (PMID 39239465, 2024). "In another murine model study, HDM triggered more eosinophilia, higher concentrations of IL-4, IL-10, and IFN-γ in BALF compared to OVA, and the author concluded that murine models triggered by HDM were more relevant to human allergic asthma." (PMID 38302925, 2024). "These cells produce transforming growth factor, IFNγ (mediator of fibrosis), IL-4, and IL-5 (mediators of IgE and eosinophilia)." (PMID 39051325, 2024). "Th2 cells produce cytokines such as IL-4, IL-5, and IL-13, which are pivotal in promoting IgE synthesis and subsequent histamine release (IL-4 and IL-13), eosinophilia (IL-5), and mucus oversecretion, airway hyperresponsiveness, and remodeling (IL-13)." (PMID 39770422, 2024).
eosinophilia (continued). "Although the model we used in the present study is characterized by prominent airway eosinophilia, the levels of Th2 cytokines, particularly IL-4 in the airways of mice, were unexpectedly low, obviously indicating non-T2 allergic airway inflammation." (PMID 39767651, 2024). "When activated by the alarmins or lipid mediators in vivo in mice, ILC2s can drive tissue eosinophilia independently of functional T cells, reflecting their potent productions of IL-5, IL-9, GM-CSF, IL-13, and, in some contexts, IL-4." (PMID 40047886, 2024). "ILC2s and a subpopulation of CD4+ T cells known as Th2 cells can secrete IL-4, IL-5, and IL-13 and stimulate type 2 immunity with high IgE antibodies and eosinophilia." (PMID 37152304, 2023). "IL-5 promotes eosinophilia, and IL-4 and IL-13 enhance the production of eosinophil chemoattractants (CCL11/eotaxin-1, CCL24/eotaxin-2, and CCL26/eotaxin-3) and activate B cells, macrophages, fibroblasts, epithelial cells, and goblet cells." (PMID 37674852, 2023). "Other investigators have also documented the importance of IL-13/IL-4 in A. fumigatus-induced pneumonia and eosinophilia in ABPA and cystic fibrosis." (PMID 38983617, 2023). "CRSwNP patients characterized by eosinophilic inflammation and type 2 inflammation have high levels of immunoglobulin (Ig) E, interleukin (IL‐5), IL‐4 and IL‐13 in local tissues, often accompanied by eosinophilia in peripheral blood." (PMID 36840493, 2023). "This suggests that the airway eosinophilia we observed in WT mice was probably driven by IL-13 and IL-4 resulting in a less overall severe eosinophilic pathology to infection, and suggesting other cell types contributed to the immunopathology observed." (PMID 37795093, 2023). "Allergic asthma is classically defined by allergen-induced airway inflammation and is represented by elevated serum immunoglobin E (IgE), type 2 cytokine (interleukins-4, -5, and -13 [IL-4, IL-5, IL-13]) production, and sputum eosinophilia (>1%-3%)." (PMID 36926031, 2023). "In the T2 endotype, there is an increase in the production of Th2 cytokines, including interleukin-4, interleukin-5, and interleukin-13, high levels of immunoglobulin-E in polyp tissue, and eosinophilia." (PMID 37674852, 2023). "For instance, Interleukin-5 (IL-5) is essential for airway eosinophilia, and Interleukin-4 (IL-4) and Interleukin-13 (IL-13) are necessary for Immunoglobulin E (IgE) production." (PMID 37781715, 2023). "Th1 cells drive a predominant cellular cytotoxic immunity mediated by IL-12/IFN-γ, whereas Th2 cells facilitate IL-4/IL-5-mediated humoral responses, notably through immunoglobulin E (IgE) production and eosinophilia." (PMID 36263051, 2022). "In this case of persistency of airway eosinophilia, it would be appropriate to consider a change of biologics toward blocking the IL-4/IL-13 pathways." (PMID 35055384, 2022). "In humans, peripheral blood eosinophilia often occurs when immunotherapy with interleukin (IL)-2, IL-4, granulocyte macrophage colony-stimulating factor, or tumor vaccine is performed." (PMID 34170380, 2022). "Th2 cytokines such as IL-4, IL-13, and IL-9 promote eosinophilia by regulating local IL-5, eotaxin synthesis, and/or inhibiting IFN-gamma production." (PMID 35805534, 2022). "On the other hand, BALB/C mice develop a predominant Th2 response, producing IL-4, IL-5, IL-6, favoring IgE production and eosinophilia." (PMID 36263051, 2022). "Polyps showing eosinophilia with an increased Th2 response (e.g., increase of IL-4 and IL-5 levels) is the dominant inflammatory endotype in Caucasian patients, while a high proportion of neutrophilic polyps is found in Asian patients." (PMID 35720287, 2022). "For example, CRS with polyps has a Type II inflammatory pattern characterized by eosinophilia and elevated IL-4, 5 and 13 cytokines." (PMID 35428368, 2022).
eosinophilia (continued). "It is upregulated by type-2 cytokines like IL-4 and IL-13 and correlates with other type-2 biomarkers such as FeNO, sputum eosinophilia, blood eosinophilia, and total IgE." (PMID 36326393, 2022). "Th2 cytokines are involved in CTCL pathogenesis of pruritus and include IL-4, IL-5 and IL-13, together with eosinophilia and IgE." (PMID 34118946, 2021). "As Il5 mRNA levels were unaffected by Ruxolitinib, yet eosinophilia was greatly reduced in SA+R mice, our observations suggest that both IL-4 and IL-13 drive eosinophilic inflammation in the lung." (PMID 34777398, 2021). "The activity of these cytokines translates into specific pathophysiological phenomena such as fibrosis (TGF-β), activation of B cells and plasma cells to IgG4 production (IL-10, IL-4, IL-5), and eosinophilia (Il-5, Il-4, Il-13)." (PMID 35145508, 2021). "The P4rr was started on GD5, which is 6–7 days after the last OVA challenge to the mothers, a time after the OVA-induced 2–5 days peak in eosinophilia and when IL4 and IL5 have resolved in OVA-challenged adult mice." (PMID 34368802, 2021). "Helminths-driven immune modulation in these conditions included reduced CD3+, CD4+, CD8+, natural killer (NK), CD4+CD25high and IFN-γ responses, but increased eosinophilia, Tregs, IL-4, IL-5 and IL-10 responses." (PMID 34220854, 2021). "CD40 signalling is important for OVA-induced eosinophilia and the production of IL-4, IL-5, and IL-13 in a mouse model of allergic asthma." (PMID 33976586, 2021). "Type-2 immunity is characterised by interleukin (IL)-4, IL-5 and IL-13, eosinophilia, mucus production, IgE, and alternatively activated macrophages (AAM)." (PMID 32457448, 2021). "The more pronounced cutaneous eosinophilia and higher IL-4 levels at 6 wpi in BB cattle suggest that a Th2-type immune response is underlying the higher susceptibility of the BB breed." (PMID 33397469, 2021). "These responses are accompanied with the induction of cytokines such as IL-4, IL-5, IL-13, and enhanced eosinophilia, and IgE responses." (PMID 34368662, 2021). "Together with the more pronounced cutaneous eosinophilia and higher IL-4 levels at 6 wpi in BB cattle, this suggests that a Th2-type immune response is underlying the more severe manifestation in the BB breed." (PMID 33397469, 2021). "Cytokines secreted by Th2 cells include IL-4, IL-5 and IL-13, which facilitate the isotope switching of antibodies, mucus secretion and eosinophilia." (PMID 34295337, 2021). "These responses are accompanied with the induction of cytokines such as IL-4, IL-5, IL-13, and increased eosinophilia, IgE as well as goblet cell hyperplasia." (PMID 34220854, 2021). "Since IL-4, IL-5, and IL-13 promote airway eosinophilia, mucus overproduction and bronchial hyper-responsiveness, it is likely that hBD-2 improves lung resistance indirectly by lowering those cytokines in the lung." (PMID 33717182, 2021). "IFN-γ, IL-4, and IL-13 concentrations in the airways were similar between WT and Bcl6ΔCD4 mice, as was eosinophilia; however, airway NK cell frequencies were elevated in Bcl6ΔCD4 mice compared with controls." (PMID 34665220, 2021). "The F1 neonates of maternal DEHP-exposed mice developed more severe allergic lung inflammation after OVA sensitization and challenge, including predominant eosinophilia and higher levels of IL-4, IL-5, and IL-13 in the BALFs, than the control F1 neonates." (PMID 33424850, 2020). "As both IL-4, and IL-5 mRNA levels are unaffected by CD2 deficiency, yet eosinophilia was greatly reduced in HDME-treated Cd2−/− mice, our observations highlight the importance of IL-13 as the central regulator of HDME-induced lung inflammation." (PMID 32477356, 2020). "The majority of white patients with CRSwNP in western countries have a type 2 pattern of inflammation characterized by pronounced eosinophilia and high levels of interleukin-4 (IL-4), IL-5 and IL-13 cytokines." (PMID 32637070, 2020).